BDNF (brain derived neurotrophic factor)
Diseases named in the same sentence as BDNF in open-access papers (continued):
Sharing a sentence is not in itself a finding about the gene and the disease.
depression (continued). "Based on the evidence that low levels of phosphorylated CREB (pCREB) are implicated in depression, and that this protein enhances BDNF transcription, it is reasonable to consider that increasing pCREB would decrease depressive symptoms." (PMID 30200269, 2018). "Diminished BDNF levels are believed to be a potential pathological mechanism underlying the impaired neurogenesis in depression." (PMID 29506545, 2018). "Authors revealed that the BDNF 66Met allele carriers with higher levels of stressful life events had a higher severity of the worst depression ever." (PMID 28822116, 2018). "Other authors proved that a reduction in BDNF expression in the dentate gyrus reduced neurogenesis and affected behaviors associated with depression." (PMID 28550529, 2018). "Although little is known about the molecular components and mechanisms involved in the stress response, increasing evidence suggests that BDNF-associated synaptic dysfunction is a key pathophysiological hallmark in depression." (PMID 30429764, 2018). "Data from previous studies have provided compelling evidence that BDNF promoters’ methylation level and histone modifications are associated with the development of depression." (PMID 29636708, 2018). "One of the central node is BDFN1, brain-derived neurotrophic factor, which is implicated in metabolic syndrome and neurodegenerative diseases like Huntington’s, Alzheimer’s, and Parkinson’s disease and depression." (PMID 30154826, 2018). "Although the neurobiological substrates of its action remain poorly documented, basic research has shown that omega-3 increases brain-derived neurotrophic factor (BDNF) levels in brain regions associated with depression, as antidepressant drugs do." (PMID 30622454, 2018). "Consistent with our previous studies, this study provides direct evidence that CUMS induced the hippocampus BDNF and neurogenesis reduction and affected behaviors associated with depression in vivo." (PMID 30323763, 2018). "Under baseline conditions, BDNF and trkB are densely-expressed in the hippocampal formation, wherein they are implicated in depression-related development of maladaptive behavior and plasticity." (PMID 30477252, 2018). "Even if it is still entirely unclear why BDNF levels in platelets or serum should reflect brain levels (see Discussion), these levels have been associated with a number of conditions including depression, Huntington’s disease, and Alzheimer’s disease." (PMID 29662942, 2018). "A growing body of evidence suggested that brain derived neurotrophic factor (BDNF) and neuroinflammation have a close association with depression-like behavior." (PMID 30410442, 2018). "Recent evidence has identified the methylation level of relative CpG islands associated with promoter I of BDNF in depression, in which the changes of DNA methylation of BDNF were postulated as a biomarker of major depression." (PMID 29636708, 2018). "Among patients with depression BDNF levels are lower and a potential mechanism of a good MedDiet adherence in lowering depression risk is through the improvement of BDNF production." (PMID 29614726, 2018). "Several lines of evidence have linked BDNF with both the pathophysiology of depression and the mode of action of antidepressants." (PMID 30459647, 2018). "The literature has documented the association of BDNF with many serious diseases, such as Alzheimer’s disease, depression, and stroke." (PMID 29390963, 2018). "We also detected the protein expression of brain-derived neurotrophic factor (BDNF) in CUMS mice, as numerous reports have underlined the fundamental role of BDNF in the pathology, physiology and treatment of depression." (PMID 30369869, 2018). "The deficiency of BDNF in the prefrontal cortex and hippocampus is known to impair brain function, which can result in depressive disorders." (PMID 30224933, 2018).
depression (continued). "The exercise group also had a significant increase in plasma brain-derived neurotrophic factor (BDNF), p = 0.003, d = 6.46, that was associated with improvements in depression scores (p = 0.002, R2 = 0.50) and sleep quality (p = 0.011, R2 = 0.38)." (PMID 29559928, 2018). "The aim of the present study was to explore the effect of electroconvulsive therapy (ECT) on serum and plasma BDNF levels and change of Montgomery–Asberg Depression Rating Scale (MADRS) and their associations in patients with major depressive disorder (MDD)." (PMID 30273985, 2018). "In animal models, chronic restraint stress is known to cause decreased BDNF expression in the hippocampus and depression-like behaviors." (PMID 29951133, 2018). "As an important nutrient for neurons, decreased release of BDNF can cause hippocampal atrophy and reduce synaptic plasticity, leading to the occurrence of depression." (PMID 28744213, 2017). "Some studies show that a decreased expression of BDNF, a key target implicated both in the etiology of depression, appears to be associated with depression symptoms both in animals and humans." (PMID 28118829, 2017). "After treatment of depression with Citalopram, BDNF levels normalize to the level of controls, while single nucleotide polymorphism (SNP) in the BDNF gene has been found to be associated with depression and bipolar disorder." (PMID 29023416, 2017). "Low levels of BDNF in depressive patients are also linked to relationship between stress and depression." (PMID 29299044, 2017). "A recent review reported decreased BDNF expression in the hippocampus of animals under chronic stress conditions (modeling depression), and suggested that downregulation of BDNF seems to be associated with an increase in anxiety-like symptoms." (PMID 35098038, 2017). "Third, no formal testing of depression or neurocognitive disorder, which are closely associated with CKD and BDNF, was performed, though medical treatment for depression was checked in the present study." (PMID 28575038, 2017). "The presence of longitudinal association between serum BDNF and depression further supports BDNF's significance." (PMID 29217995, 2017). "Brain-derived neurotrophic factor (BDNF) is one of the best studied neurotrophic factors implicated in depression and antidepressant effect." (PMID 29075536, 2017). "This is important given that reduced BDNF levels in the human brain has been associated with depression, while treatment with an anti-depressant increased BDNF and improved symptoms of depression." (PMID 28304335, 2017). "Reduced serum levels of brain-derived neurotrophic factor (BDNF) have been implicated in depression, bipolar disorder, and dementia." (PMID 29127487, 2017). "Decreased BDNF levels have been associated with psychiatric and neurological disorders including anxiety, depression and Alzheimer’s disease, as well as emotional exhaustion and burnout." (PMID 28694775, 2017). "The neurotoxic effects of depression include atrophy of hippocampus linked to over secretion of cortisol or abnormally low concentration of brain-derived neurotrophic factor (BDNF)." (PMID 29410733, 2017). "Stress is a potent risk factor for depression and is associated with decreased BDNF concentration in animal models." (PMID 29299044, 2017). "A common functional polymorphism in the BDNF gene (termed the Val66Met polymorphism) has been found to interact with stress exposure to affect risk of depression, bipolar disorders, schizophrenia, or suicide." (PMID 28620285, 2017). "BDNF levels were reduced following treatment with IFN-alpha, and lower pretreatment BDNF was associated with higher depression symptoms." (PMID 29019461, 2017). "The present study revealed that repeated ethanol administration caused depression-like behaviors together with the subtle reductions of BDNF levels in the hippocampus and prefrontal cortex." (PMID 28837087, 2017).
depression (continued). "Stress, considered a major risk factor for depression, decreases BDNF and its downstream signalling in the hippocampus and cerebral cortex." (PMID 28134845, 2017). "Alternation in BDNF levels have been implicated in psychiatric disorders, including depression and substance abuse, as well as neurodegenerative disorders, such as Alzheimer’s, Parkinson’s and Huntington’s diseases." (PMID 28761074, 2017). "Accordingly, decreased BDNF levels have been reported in patients with depression, and a recent meta-analysis showed that altered peripheral BDNF levels are associated with ongoing depressive disorders." (PMID 28539884, 2017). "Decreased plasma BDNF levels were related to depression, bipolar disorder, and anxiety, whereas increased BDNF levels were found to be associated with smoking." (PMID 29109736, 2017). "BDNF is the best studied neurotrophic factor implicated in depression, which is also concerned to neuroplasticity and memory." (PMID 28118829, 2017). "As an example, subjects with both the G/G genotype in the 5-HT1AR promoter and at least one copy of the Met allele of the BDNF Val66Met polymorphism had a greater than three times higher risk of treatment resistant depression." (PMID 28646910, 2017). "Reduced levels of BDNF have been consistently associated with depression, whereas normalization of BDNF levels has been reported following antidepressant treatment." (PMID 29225330, 2017). "Recently, BDNF has been implicated as a possible biomarker for psychiatric diseases such as schizophrenia, bipolar disorder and major depression, given that BDNF levels are lower in these patients than in healthy subjects." (PMID 28638711, 2017). "Lentiviral knockdown of BDNF in the hippocampus has been shown to reduce neurogenesis and precipitate behaviors associated with depression." (PMID 35098038, 2017). "Previous studies indicated that decrease in BDNF is associated with stress disorders and depression." (PMID 29317891, 2017). "Accordingly, the hippocampal volume is reduced in patients with post‐traumatic stress disorder (Angelucci, Brene, & Mathe, 2005), and with depression associated with the BDNF Met polymorphism, which is known to be less active than its normal variant." (PMID 29075579, 2017). "Our findings illustrate a possible mechanism involving BDNF–5-HT2A signaling pathways by which ApoE isoforms confer differential risk for depression." (PMID 28934977, 2017). "Another widely studied genotype in depression is the Val66Met polymorphism of the gene for the brain-derived neurotrophic factor (BDNF) that plays a major role in neuroplasticity." (PMID 29019461, 2017). "Although the links between depression, stress, antidepressants and BDNF are well recognized, the mechanisms underlying their interactions are still not soundly established." (PMID 29141007, 2017). "Decreased BDNF levels were shown to parallel progression of depression, inhibit neurogenesis, while causing structural and functional changes in the hippocampus." (PMID 29217995, 2017). "One study of postmortem brain samples implicated BDNF as a factor in the pathophysiology of depressive disorders." (PMID 28348623, 2017). "Keller and colleagues demonstrated that BDNF promoters’ DNA methylation changes in brain are associated with major depression and suicide." (PMID 27267954, 2016). "PGE2 has been demonstrated in inflammatory conditions to upregulate phosphodiesterase-4, which in turn inhibits downstream formation of BDNF, which itself is implicated in depression." (PMID 26483037, 2016). "Examining the concomitant effects of another polymorphism (C1019G) from the serotonin receptor gene, 5HT1A and the Val66Met polymorphism of the BDNF gene revealed increased risk for depression when expressing both risk variants." (PMID 28096796, 2016).
depression (continued). "Adolescents exposed in utero to maternal smoking show an increased DNA methylation of the BDNF gene promoter with previous studies indicating that a methylated BDNF gene acts as a diagnostic biomarker of depression." (PMID 27077873, 2016). "BDNF DNA methylation patterns have also been associated with depression severity, and the presence of suicidal ideation in MDD subjects." (PMID 27199779, 2016). "A number of studies have indicated that decreased levels of BDNF are associated with depression and become enhanced following antidepressant treatment." (PMID 27253067, 2016). "In contrast,inactivity and low circulating BDNF levels are associated with many chronic disorderssuch as obesity, type 2 diabetes, cardiovascular diseases, depression, dementia andcognitive impairment." (PMID 27332774, 2016). "In this study, we attempt to explore the mechanism underlining the effect of AS extracts on CUMS induced depression in rats by assaying hippocampal BDNF protein expression levels and the phosphorylation of CREB and ERK 1/2." (PMID 27642354, 2016). "Previous studies have showed the BDNF Val66Met polymorphism moderates the relationship between history of childhood adversity and depression outcomes." (PMID 27621711, 2016). "BDNF signaling has a pivotal role in hippocampal neuroprotection, neurogenesis, and affects depression-associated behaviors." (PMID 27375434, 2016). "Consistent with the previous studies, our results showed that the expression of BDNF protein decreased in rats exposed to CUMS, which demonstrated that the depression-like behaviors induced by CUMS were associated with BDNF protein in the hippocampus." (PMID 27680977, 2016). "It is possible that BDNF affects depression only via the interaction with other polymorphisms or steroid secretion." (PMID 28096796, 2016). "The prefrontal cortex is involved in the regulation of mood and stress, and changes in the expression of BDNF and 5-HT in the prefrontal cortex have been implicated in the pathophysiology of depression and the therapeutic effect of antidepressants." (PMID 28119573, 2016). "Supporting this theory, several groups have illustrated how BDNF genotypic variations were associated with risk for depression." (PMID 27199779, 2016). "This study demonstrated a significant association between depression and methylation levels of BDNF at specific CpG sites." (PMID 27199779, 2016). "There have been increasing evidences more directly supporting the association between peripheral BDNF methylation and depression." (PMID 26876488, 2016). "BDNF promoter methylation was shown to be associated with cortical thickness in patients with recurrent major depression." (PMID 28096796, 2016). "In humans, reduced BDNF function is implicated in the pathophysiology of a range of neurological, affective and psychiatric disorders, including major depressive disorder, post‐traumatic stress disorder (PTSD) and schizophrenia." (PMID 26586578, 2016). "Exercise induces beneficial responses in the brain, which is accompanied by an increase in BDNF, a trophic factor associated with cognitive improvement and the alleviation of depression and anxiety." (PMID 27253067, 2016). "Like STEP, BDNF is expressed in the central nervous system and has been implicated in a variety of neuropsychiatric disorders, including major depressive disorder, bipolar disorder, and schizophrenia." (PMID 26872063, 2016). "Brain-derived neurotrophic factor (BDNF) has been shown to mediate neurogenesis and synaptic plasticity, which is implicated in depression pathogenesis." (PMID 27680977, 2016). "In particular, Brain-Derived Neurotrophic Factor (BDNF), a brain plasticity marker, has been extensively investigated and associated with stress response, depression, and anxiety." (PMID 26881124, 2016).
depression (continued). "Consistently, human adults who have experienced abuse during childhood and adolescence demonstrate an increased susceptibility to the development of depression and also present with lower salivary BDNF levels." (PMID 27757074, 2016). "The Val66Met polymorphism in the brain-derived neurotrophic factor (BDNF) gene causing deficient BDNF protein secretion affects the neuroplasticity processes crucial for depression." (PMID 28096796, 2016). "In two subsequent studies, authors found a significant association between the BDNF promoter VI methylation levels and late-life depression as well as depression related to breast cancer." (PMID 27267954, 2016). "In particular, BDNF signaling in the mammalian hippocampus has been implicated in learning and memory through its effect on long-term potentiation and depression." (PMID 26909029, 2016). "Brain-derived neurotrophic factor has recently become the focus of methylation studies associated with depression." (PMID 28096796, 2016). "In order to further confirm the effects of depression on the central nervous system (CNS) in patients with SCLC, we measured the serum BDNF levels and found that increased depression was associated with significant decreases in BDNF levels." (PMID 27852063, 2016). "In Slovak population, TT genotype of C677T and AC genotype of A1298C of BDNF gene are considerably associated with the higher risk of major depression disorders." (PMID 27478487, 2016). "The BDNF signalling system has been associated with depression and regulates neuronal plasticity and survival." (PMID 27456456, 2016). "The BDNF rs1491850 has also been implicated in treatment response phenotypes and remission status in major depressive disorder." (PMID 26708060, 2016). "Reduced promoter IV-driven expression of brain-derived neurotrophic factor (BDNF) is implicated in stress and major depression." (PMID 27648918, 2016). "Here, we found that CSDS stress robustly decreased the BDNF expression in both the hippocampus and mPFC, two regions closely implicated in the pathogenesis of depression." (PMID 25618406, 2015). "To add to the emerging literature, we sought to evaluate the extent to which serum BDNF levels are associated with antepartum depression among pregnant Peruvian women." (PMID 25886523, 2015). "In depression, higher percentages of female participants were associated with a small increase in BDNF levels." (PMID 26621529, 2015). "A recent meta-analysis of the interaction between the BDNF Val66Met polymorphism and stress in depression contained 22 studies with a mean age range from 8.85–65 years." (PMID 26733829, 2015). "As one of the largest studies investigating methylation in depression, our findings add further support for the role of differential BDNF methylation, and suggest that genetic variation in BDNF mediates these associations." (PMID 26285129, 2015). "In contrast, studies investigating stressful life events found higher depression among Korean older adults and maltreated children with BDNF Met and 5HTTLPR S′ allele." (PMID 25781924, 2015). "In combination with exposure to ELS events, both SLC6A4 and BDNF polymorphisms have been attributed to increased risk for depression in later life." (PMID 26583053, 2015). "Future studies designed to evaluate the role of alterations in BDNF signalling in PD-associated depression and its putative significance as a biomarker of this disease are warranted." (PMID 25739024, 2015). "Low levels of serum BDNF are associated with a dispositional vulnerability to depression and with acute depressive states in the general population." (PMID 25908105, 2015). "A clinical study demonstrated that stress-related psychiatric disorders including depression and anxiety, are associated with reduced brain BDNF and its receptor TrkB levels." (PMID 26138544, 2015).